FEZF2 (FEZ family zinc finger 2)
Description:
Transcription repressor. Required for the specification of corticospinal motor neurons and other subcerebral projection neurons. May play a role in layer and neuronal subtype-specific patterning of subcortical projections and axonal fasciculation. Controls the development of dendritic arborization and spines of large layer V pyramidal neurons. May be involved in innate immunity (By similarity).
Synonyms: FEZL; ZNF312; FKSG36; FLJ10142; TOF; Zfp312; FEZ
Tractability: No criterion of Open Targets' tractability assessment is met for any kind of drug.
Gene: Protein-coding gene on chromosome 3 (62,369,681 to 62,374,473, reverse strand). Ensembl gene ENSG00000153266.
Subcellular location: Nucleus
Subcellular location (Human Protein Atlas): Nucleoplasm; Vesicles; Centrosome; Cytosol
Gene Ontology:
Molecular function: chromatin binding; DNA-binding transcription activator activity, RNA polymerase II-specific; DNA-binding transcription repressor activity, RNA polymerase II-specific; RNA polymerase II cis-regulatory region sequence-specific DNA binding; sequence-specific DNA binding; transcription cis-regulatory region binding
Biological process: regulation of gene expression; cell dedifferentiation; negative regulation of cell population proliferation; negative regulation of transcription by RNA polymerase II; positive regulation of DNA-templated transcription; positive regulation of transcription by RNA polymerase II; regulation of neurogenesis; telencephalon development
Cellular component: nucleus
Genetic constraint (gnomAD): Loss-of-function variants: 2 observed, 27.69 expected, observed/expected ratio (o/e) 0.0722, 90% interval 0.029 to 0.23. The synonymous counts are far from expectation, so gnomAD's model fits this gene poorly and the ratio says little. Missense variants: 516 observed, 578.7 expected, observed/expected ratio (o/e) 0.89, 90% interval 0.83 to 0.96. Synonymous variants: 322 observed, 264.13 expected, observed/expected ratio (o/e) 1.22, 90% interval 1.11 to 1.34.
Homologues: Orthologues: macaque FEZF2 (99% identical), rabbit FEZF2 (99% identical), dog FEZF2 (98% identical), guinea pig FEZF2 (98% identical), chimpanzee FEZF2 (98% identical), mouse Fezf2 (95% identical), rat Fezf2 (94% identical), pig FEZF2 (83% identical), tropical clawed frog fezf2 (73% identical), zebrafish fezf2 (67% identical). Paralogues in human: FEZF1 (54% identical), ZBTB49 (26% identical), BCL6 (18% identical), ZNF683 (18% identical), ZBTB7B (17% identical), ZNF280D (17% identical), ZNF280C (16% identical), BCL6B (15% identical), PRDM13 (15% identical), ZBTB14 (15% identical), ZNF280B (15% identical), GFI1 (14% identical), and 16 more.
Diseases named in the same sentence as FEZF2 in open-access papers:
FEZF2 is named in the same sentence as 29 diseases in open-access papers, as found by Europe PMC text mining. Sharing a sentence is not in itself a finding about the gene and the disease. The quoted sentences say what the papers report.
mastitis (5 papers, 2009 to 2024). Inflammation of breast tissue during lactation or postpartum due to an obstructed duct or infection. "Yet, FEZF2 found upstream from the rs383806754 has been linked with mastitis in other studies." (PMID 37685039, 2023). "The expression of the FEZF2 gene on BTA22 has been reported to be induced by mastitis and its sequence variation is associated with mastitis resistance or susceptibility; cows susceptible to mastitis have a three-base insertion in a glycine-coding stretch of the gene." (PMID 19508288, 2009).
autoimmune disease (4 papers, 2021 to 2023). A disorder resulting from loss of function or tissue destruction of an organ or multiple organs, arising from humoral or cellular immune responses of the individual to their own tissue constituents. "The FEZF2 was suggested to be involved in immune tolerance and defects of the gene, causing autoimmune diseases in humans." (PMID 37685039, 2023). "The repressed genes in Fezf2 -/- mTECs are reported to be associated with TSAs in autoimmune diseases or tumors." (PMID 36110862, 2022). "It is well-established that mutation of Aire results in multiple organ-specific autoimmune diseases, and mice with Fezf2 deficiency in mTECs also develop a severe autoimmune phenotype, which is thought to result from a failure of the given thymic TSA expression under the control of Aire or Fezf2." (PMID 36110862, 2022). "In this review, we compare the roles of Aire and Fezf2 in regulating TSAs, with an emphasis on their molecular mechanisms in autoimmune diseases, which provides the foundation for devising improved diagnostic and therapeutic approaches for patients." (PMID 36110862, 2022). "Here, we review some of the recent progress in our understanding of individual TSAs whose thymic expression is regulated by Aire or Fezf2, which are critical for specific autoimmune diseases." (PMID 36110862, 2022). "This review will provide a comprehensive description of the role of Aire or Fezf2 in thymic TSA expression and their effects on autoimmune diseases." (PMID 36110862, 2022).
Autoimmunity (4 papers, 2017 to 2024). The occurrence of an immune reaction against the organism's own cells or tissues. "Furthermore, AIRE and FEZF2 mutations are associated with the development of autoimmunity in peripheral organs." (PMID 31008523, 2019). "Unsurprisingly, loss of expression of these PTAs, which is driven by the transcription factors autoimmune regulator (AIRE), deformed epidermal autoregulatory factor 1 (DEAF1), and FEZ family zinc finger 2 (Fezf2), leads to autoimmunity." (PMID 32784936, 2020). "Many studies, including the discovery of the transcription factors autoimmune regulator (AIRE) and fasciculation and elongation protein zeta family zinc finger (FEZF2), have shown that a defect in thymus central self‐tolerance is the earliest event promoting autoimmunity." (PMID 31008523, 2019). "A general defect in intrathymic expression of tissue-restricted antigens, for instance in Aire- or Fezf2-deficient mice, or the selective interference with intrathymic expression of individual genes, as is the case for the eye autoantigen IRBP, can precipitate spontaneous autoimmunity." (PMID 29170668, 2017).
autism (2 papers, 2021 to 2023). Persistent deficits in social interaction and communication and interaction as well as a markedly restricted repertoire of activity and interest as well as repetitive patterns of behavior. "Importantly, human genetic studies have also identified Fezf2 as an autism candidate gene, suggesting the involvement of the Fezf2-dependent cellular lineage in neurodevelopmental disorders." (PMID 36214963, 2023).
epilepsy (2 papers, 2020 to 2022). A brain disorder characterized by episodes of abnormally increased neuronal discharge resulting in transient episodes of sensory or motor neurological dysfunction, or psychic dysfunction. "Thus, activating Rorb or Fezf2 in astrocytes, for example, by gene therapy approaches, might reduce seizure susceptibility in epilepsy." (PMID 35546493, 2022). "Thus, L2–3_Cux2 and L5–6_Fezf2 subtypes co-clustered with Sst_Tac1 and Vip_Cbln1 subtypes, whereas L3_Cux2_Prss12 co-clustered with Pvalb_Sulf1, which might underlie local neuronal networks with most strongly affected in the epilepsy transcriptome." (PMID 33028830, 2020).
nasopharyngeal carcinoma (2 papers, 2015 to 2017). A carcinoma arising from the nasopharyngeal epithelium. "In accordance with our findings, FEZF2 is a known tumor suppressor gene in mature tissue, with the silencing of FEZF2 expression causative of nasopharyngeal carcinoma and implicated in brain tumors." (PMID 28936162, 2017).
thymoma (2 papers, 2023). A neoplasm arising from the epithelial cells of the thymus. "Furthermore, HIPK2, HDAC9, and FEZF2 displayed a significantly higher expression in thymic carcinomas than in thymomas in both datasets." (PMID 38201543, 2023).
Anxiety (1 paper, 2024). Intense feelings of nervousness, tension, or panic often arise in response to interpersonal stresses. "Within the ZNF family, FEZ zinc finger 1 (FEZF1), FEZ zinc finger 2 (FEZF2), ZNF, and FOG family member 1 (ZFPM1) contribute to the development and function of neural circuits, which are crucial for fear, anxiety, and behavioral regulation." (PMID 39595393, 2024).
autism spectrum disorder (1 paper, 2017). A spectrum of developmental disorders that includes autism, and Asperger syndrome. "Tbr1 has been associated with autism spectrum disorders, regulates corticofugal cell identities during development, and represses target genes including Fezf2 during development of the corticospinal tract." (PMID 28112643, 2017).
Hypercalcemia (1 paper, 2021). An abnormally increased calcium concentration in the blood. "Taken together, lower lnc-FEZF2–9:2 may participate in hypercalcemia via PDE7-VDR pathway, which also need further molecular study to be proven." (PMID 33910638, 2021).
juvenile idiopathic arthritis (1 paper, 2021). Juvenile idiopathic arthritis (JIA) is the term used to describe a group of inflammatory articular disorders of unknown cause that begin before the age of 16 and last over 6 weeks. "However, some Fezf2-dependent TRAs identified in mice are autoantigens in humans, including aquaporin 8 (AQP8) in Sjögren syndrome and transthyretin (TTR) in juvenile idiopathic arthritis (JIA)." (PMID 33537838, 2021).
nasopharyngeal squamous cell carcinoma (1 paper, 2017). A squamous cell carcinoma that arises from the nasopharynx. "FEZF2 was found to be a 3p14 TSG that is frequently methylated in nasopharyngeal squamous cell carcinoma." (PMID 27926516, 2017).
parathyroid cancer (1 paper, 2021). "Tumor suppressor fragile histidine triad (FHIT), a target gene for lnc-FEZF2–9:2, was also down-regulated in parathyroid cancer." (PMID 33910638, 2021).
Parkinson disease (1 paper, 2022). A progressive degenerative disorder of the central nervous system characterized by loss of dopamine producing neurons in the substantia nigra and the presence of Lewy bodies in the substantia nigra and locus coeruleus. "Fezf2 is sufficient to increase dopaminergic neurons, and its defective expression may contribute to the progression of disease phenotypes such as Parkinson’s disease." (PMID 36110862, 2022).
schizophrenia (1 paper, 2021). A major psychotic disorder characterized by abnormalities in the perception or expression of reality. "For example, Fezf2 is a transcription repressor that is implicated in the development of dendritic arborization and spines of large L5 pyramidal neurons a population of neurons affected in schizophrenia." (PMID 33495243, 2021).
thymic carcinoma (1 paper, 2023). Thymic carcinoma (TC) is a type of thymic epithelial neoplasm characterized by a high malignant potential. "Therefore, we investigated the correlation between methylation and mRNA expression status in the genes newly identified as activated or suppressed in thymic carcinomas, specifically HIPK2, HDAC9, NFATC1, PAX9, and SIX1 (the methylation status of FEZF2 was not available in the dataset)." (PMID 38201543, 2023).
infection (1 paper, 2021). The state of being infected such as from the introduction of a foreign agent such as serum, vaccine, antigenic substance or organism. "Analysis revealed that relative AIRE and FEZF2 protein levels did not change following infection compared to mock-infected thymuses." (PMID 34361972, 2021). "In utero CV-B4 infection did not induce any significant change in the level of Aire and Fezf2 transcripts." (PMID 34361972, 2021).
psychiatric disorder (1 paper, 2021). A disorder characterized by behavioral and/or psychological abnormalities, often accompanied by physical symptoms. "It is of note that FEZF2 is a gene with a potentially high severity level in psychiatric disorders, as evaluated by our published database." (PMID 33801746, 2021).
FEZF2 also shares sentences with these, for which no sentence is quoted: neoplastic diseases (2 papers); alcohol dependence (1); bladder tumors (1); brain tumors (1); Hashimoto thyroiditis (1); hydrocephaly (1); neurodevelopmental disorder (1); rheumatoid arthritis (1); Sandhoff disease (1); Sjögren’s syndrome (1); type 1 diabetes (1).